ADIPOR1 (adiponectin receptor 1)
Diseases named in the same sentence as ADIPOR1 in open-access papers (continued):
Sharing a sentence is not in itself a finding about the gene and the disease.
uveal melanoma (1 paper, 2025). A melanoma derived from melanocytes of the uveal tract. "These include creating an adiponectin-deficient environment, which limits the binding of Adipor1, the receptor of adiponectin, to uveal melanoma cells to exert its antitumor functions." (PMID 40862816, 2025).
viral infection (1 paper, 2023). "Therefore, the down-regulation of ADIPOR1 expression in the infected group may be an important factor contributing to inflammation after viral infection." (PMID 37896902, 2023).
vitiligo (1 paper, 2018). Generalized well circumscribed patches of leukoderma that are generally distributed over symmetric body locations and is due to autoimmune destruction of melanocytes. "Due to this phenotypic mimicry and since the vitiligo mouse model appears to have a dysfunction in retinoid metabolism, this data presents an exciting hypothesis for whether ADIPOR1 functions to control retinoid levels as well." (PMID 30254279, 2018).
ZIKV infection (1 paper, 2023). "Taken together, these observations point to the potential beneficial effect of AdipoR1/AMPK pathway stimulation during ZIKV infection." (PMID 38257725, 2023). "The role of metabolic reprogramming induced during ZIKV infection on AdipoR1/R2 expression then needs to be clarified." (PMID 38257725, 2023). "To investigate the involvement of adiponectin signaling in limiting the infectious process, we analyzed the expression levels of genes in the AdipoR1/AMPK pathway under different conditions of ZIKV infection and AdipoRon treatment." (PMID 38257725, 2023). "Although AdipoR1 and AdipoR2, the main receptors for adiponectin, are known to be ubiquitously expressed, we first ensured that it was the case in our A549 cell model of ZIKV infection." (PMID 38257725, 2023). "Then, one explanation for the decrease in ADIPOR1/R2 expression following ZIKV infection could be the virus-induced metabolic reprogramming toward aerobic glycolysis." (PMID 38257725, 2023). "Hypothesizing that the cytoprotective action of AdipoRon could favorably influence the outcome of ZIKV infection, we found in our in vitro infection model of A549 cells expressing adiponectin receptors (mainly ADIPOR1 and to a lesser extent ADIPOR2) that AdipoRon was indeed able to limit infection." (PMID 38257725, 2023). "Unexpectedly, while treatment with AdipoRon led to the upregulation of both ADIPOR1 and CPT1 expression, we observed that the transcriptional expression of both genes was halved under a 48 h ZIKV infection condition." (PMID 38257725, 2023).
cancer (41 papers, 2011 to 2025). A tumor composed of atypical neoplastic, often pleomorphic cells that invade other tissues. "Our findings are therefore a critical contribution to the literature because they provide strong evidence that the same ADIPOR1 SNP can exert more or less influence on cancer risk depending on the type of cancer and ethnicity." (PMID 26047008, 2015). "Circulating adiponectin levels are influenced primarily by the activity of adiponectin receptors 1 and 2 (ADIPOR1, ADIPOR2), and some studies have linked ADIPOR1 dysfunction with development of cancer." (PMID 26047008, 2015). "Although they are not strongly correlated with tumor mutation burden (TMB) or microsatellite instability (MSI), ADIPOR1/2 genes display a significant association with cancer stemness, tumor immune microenvironment, immune checkpoint genes (especially CD274 and NRP1), and drug sensitivity." (PMID 36896172, 2023). "In addition, adiponectin receptor 1 (AdipoR1) and adiponectin receptor 2 (AdipoR2), the main regulators of adiponectin, have been implicated in carcinogenesis in several cancers, including RCC." (PMID 28178338, 2017). "Overall and subgroup analysis of the ADIPOR1 rs7539542(C/G) polymorphism and cancer risk." (PMID 26047008, 2015). "PubMed, EMBASE, Cochrane Library, the Chinese Biological Medical Database and the Chinese National Knowledge Infrastructure Database were systematically searched to identify all case-control studies published through February 2015 examining any ADIPOR1 polymorphisms and risk of any type of cancer." (PMID 26047008, 2015). "Despite numerous studies of the possible association of ADIPOR1 SNPs rs12733285(C/T), rs1342387(G/A) and rs7539542(C/G) with cancer risk, whether these polymorphisms are indeed associated with cancer risk remains unclear." (PMID 26047008, 2015). "Overall and subgroup analysis of the ADIPOR1 rs1342387(G/A)polymorphism and cancer risk." (PMID 26047008, 2015). "Overall and subgroup analysis of the ADIPOR1 rs1342387(G/A)polymorphism and cancer risk in Asians." (PMID 26047008, 2015). "Studies have come to conflicting conclusions about whether polymorphisms in the adiponectin receptor 1 gene (ADIPOR1) are associated with cancer risk." (PMID 26047008, 2015). "Overall and subgroup analysis of the ADIPOR1 rs12733285(C/T) polymorphism and cancer risk." (PMID 26047008, 2015). "Cancer cells deficient in AdipoR1 metastasized to the lymphatic system and the peritoneal cavity." (PMID 23691481, 2012). "ADIPOR1 was mildly overexpressed in cancer tissue, suggesting a role in the altered metabolic signaling in the tumor, while ADIPOR2 remained unchanged, possibly indicating a more stable or non‐dominant role in this context." (PMID 40642843, 2025). "In contrast, ADIPOR1 was mildly over‐expressed in the cancer tissue, whereas ADIPOR2 showed similar expression to the control sample." (PMID 40642843, 2025). "Associations between Adiponectin receptors (ADIPOR1 and ADIPOR2) and cancer characteristics are plotted using Least Square means (LS means)." (PMID 40642843, 2025). "determined that AdipoR1 was expressed in 27% of primary malignant tumors, while AdipoR2 was found in 47% of primary malignant tumors via immunohistochemical staining of 49 thyroid tumor samples and metastatic lymph nodes." (PMID 38800384, 2024). "Other alterations in the ApN signalling cascade were observed, notably an increased AdipoR1 expression and a decreased AdipoR2 expression in the liver of cancer mice." (PMID 38572511, 2024). "(ii) Dysregulation of gene ADIPOR1 (in cluster-3) is widely observed in many cancers, but its genomic alteration frequencies are low45." (PMID 39013885, 2024). "ADIPOR1 was predominantly upregulated in cancers, whereas ADIPOR2 was downregulated in many cancers." (PMID 36896172, 2023). "Considering the complex biological functions of AdipoR1 and AdiopoR2, there is an urgent need to thoroughly analyze their contribution in cancer and anti-cancer immunity." (PMID 36896172, 2023).
cancer (continued). "ADIPOR1 and ADIPOR2 play critical roles in diverse cancers, and it is a potential strategy to treat tumors through targeting ADIPOR1 and ADIPOR2." (PMID 36896172, 2023). "Except for cancer, during hepatic lipid metabolism, miR-5194 distributing in the mitochondria activated ADIPOR1/PPARA signaling that sequentially accelerated fatty acid oxidation." (PMID 37215458, 2023). "Nevertheless, more research is needed to fully understand the connections between ADIPOR1/2 and cancer stem cells." (PMID 36896172, 2023). "CD274, encoding PD-L1, was observed significantly correlated with ADIPOR1 and ADIPOR2 in almost all the cancers." (PMID 36896172, 2023). "Our study revealed that both ADIPOR1 and ADIPOR2 were positively associated with CD4+ T cell and negatively associated with NK cell in most cancers." (PMID 36896172, 2023). "The current study indicated that the promoter DNA methylation levels of ADIPOR1/2 were rarely dysregulated in most cancers." (PMID 36896172, 2023). "CUR also inhibits adiponectin receptor 1, preventing cancer cells from migrating and invading their host." (PMID 37697969, 2023). "Although they possessed significant correlations across cancers, the expression patterns of ADIPOR1 and ADIPOR2 were varied." (PMID 36896172, 2023). "Here, we conducted a pan-cancer analysis to investigate the roles of AdipoR1 and AdiopoR2 across cancers." (PMID 36896172, 2023). "In order to adequately address ADIPOQ’s numerous roles in cancer and immunity, the research focus has shifted toward its receptors: ADIPOR1, ADIPOR2 and T-cadherin." (PMID 36429712, 2022). "Recent studies have proposed AdipoRon, a synthetic analog of adiponectin that acts on AdipoR1 and AdipoR2 receptors, as an anticancer drug to treat several types of cancer, especially PDACs." (PMID 36558998, 2022). "Accumulating evidence has shown that the expression of AdipoRs (AdipoR1 and AdipoR2) can be observed in human cancer tissues." (PMID 33752745, 2021). "Such potent anti-cancer potential of adiponectin is also reflected from the fact that the expression of adiponectin receptor 1 and 2 is downregulated in highly metastatic cancers." (PMID 34588926, 2021). "AdipoR1 (one of the adiponectin receptors), has been of interest in cancer research because of its anti-tumorigenic role described when interacting with its ligand." (PMID 31534630, 2019). "Adiponectin is a mammalian hormone that exerts anti-diabetic, anti-cancer and cardioprotective effects through interaction with its major ubiquitously expressed plasma membrane localized receptors, AdipoR1 and AdipoR2." (PMID 23762377, 2013). "They reported that APN suppresses cancer cell proliferation in vitro, as mediated by AdipoR1 and -R2." (PMID 23691481, 2012). "Dose-dependent effects of ADP 355 were tested in different cancer cells lines expressing AdipoR1 and AdipoR2." (PMID 21974986, 2011). "AdipoR1 and AdipoR2 were positively detected in the cytoplasm as well as the cell membrane of cancer cells." (PMID 22078265, 2011). "Notably, several of these biomarker genes, including ADIPOR1 (which mediates increased AMP-activated protein kinase and PPARα ligand activity, thereby negatively regulating cancer cell progression, have been previously implicated in GC." (PMID 41264656, 2025). "We conducted a comprehensive pan-cancer analysis for the roles of AdipoR1 and AdipoR2 via several public databases, including expression differences, prognostic value, and the correlations with tumor microenvironment, epigenetic modification, and drug sensitivity." (PMID 36896172, 2023). "The dysregulation of ADIPOR1/2 is observed in various cancers." (PMID 36896172, 2023). "The protein levels of ADIPOR1/2 in most cancers need to be validated by experiments." (PMID 36896172, 2023). "Data on ADIPOR1/2 proteins in cancer tissues were supplied from the UALCAN database." (PMID 36896172, 2023). "In many cancers, subtype C4 (lymphocyte depleted) expressed higher ADIPOR1." (PMID 36896172, 2023).
cancer (continued). "Finally, subjects were genotyped for polymorphisms of interest, considering that ADIPOQ and ADIPOR1 SNPs can cause the improper functioning of the ADIPOQ axis and have important clinical implications for cancer development." (PMID 36429712, 2022). "Most of the biological effects of Acrp30 are mediated by its receptors, AdipoR1 and AdipoR2, which belong to the seven-transmembrane-domain receptor family and have been shown to have abnormal expression in various types of human cancer." (PMID 33752745, 2021). "Whether Adiponectin Receptor 1 and 2 play different roles in this context is unknown, although recently it has been shown that the two receptors extert opposite effects on cancer progression." (PMID 30271669, 2018). "For many genes, their function in cancer is still unknown while some others have already been implicated in cancer such as: RABIF, KLHL12, ADIPOR1, CYBR5R1 and PRELP." (PMID 29844869, 2018). "Adiponectin receptor 1 and 2 were often differentially expressed in cancers." (PMID 27768592, 2016). "Other studies investigated the role of AdipoR1 and -R2 in cancer prognosis." (PMID 23691481, 2012). "Hence, there is an urgent need to explore the roles of AdipoR1 and AdipoR2 in cancers." (PMID 36896172, 2023). "However, among cancers, the frequency of ADIPOR1/2 genetic alterations was low." (PMID 36896172, 2023). "In addition, the protein abundance of ADIPOR1/2 was observed dysregulated in many cancers as well." (PMID 36896172, 2023). "However, a negative association was witnessed between ADIPOR1 rs2232853 variant and cancer risk (allele contrast: OR 0.638, 95%CI 0.535-0.760)." (PMID 27768592, 2016). "Intriguingly, the adiponectin receptors, ADIPOR1 and ADIPOR2 demonstrated opposing correlations with cancer characteristics such as grade, histology, LVSI, and microcystic elongated and fragmented (MELF) pattern." (PMID 40642843, 2025). "Both ADIPOR1 and ADIPOR2 genes are dysregulated in most cancers, but their genomic alteration frequencies are low." (PMID 36896172, 2023). "In summary, ADIPOR1 and ADIPOR2 display the capacity to influence anti-cancer immunity and play vital roles in numerous tumors." (PMID 36896172, 2023). "Both ADIPOR1 and ADIPOR2 exhibited correlations with diverse immune checkpoint genes in various cancers." (PMID 36896172, 2023). "ADIPOR1 and ADIPOR2 were correlated with stemness in many cancers, even though they only had weak correlations with TMB and MSI." (PMID 36896172, 2023). "Although we conducted a comprehensive analysis for the diverse roles of ADIPOR1 and ADIPOR2 across cancers, further experimental evidences are required to identify our results." (PMID 36896172, 2023). "To investigate the functions of ADIPOR1 and ADIPOR2 genes in tumors, we carried out a thorough pan-cancer analysis." (PMID 36896172, 2023). "According to the GSE44076 dataset analysis, ADIPOR1 mRNA levels were increased in primary tumors when compared to adjacent normal colon mucosa, while ADIPOR2 mRNA levels were decreased in cancer (p < 0.0001)." (PMID 36429712, 2022). "Immunohistochemical analysis of human and murine PDAC tumors showed a downregulation of both adiponectin receptors, ADIPOR1 and ADIPOR2, in cancer compared to adjacent normal acinar tissue." (PMID 29156726, 2017). "Consequently, a total of 11 studies were enrolled in the meta-analysis investigating the relationships between LEP/LEPR/ADIPOQ/ADIPOR1/ADIPOR2 variants and total PCa risk, and ten studies were included in the pooled-review discussing these polymorphisms' impact on the aggressiveness of cancer." (PMID 27768592, 2016). "Notably, ADIPOR1 and ADIPOR2 showed opposite correlations with cancer traits like grade, histology, and LVSI." (PMID 40642843, 2025). "Further, ADIPOR1 mRNA expression was observed in both tissues, but was higher in tumour tissues from women with BC than in those without this cancer." (PMID 41456223, 2025). "Some studies have focused on how ADIPOR1 and ADIPOR2 affect cancer prognosis." (PMID 36896172, 2023).
cancer (continued). "Low genetic alteration frequency was seen for both ADIPOR1 and ADIPOR2 across cancers." (PMID 36896172, 2023). "Hence, using a number of public databases, we carried out this study to explore the roles of ADIPOR1 and ADIPOR2 across cancers." (PMID 36896172, 2023). "ADIPOR1 and ADIPOR2 exhibited a wide positive correlation across cancers." (PMID 36896172, 2023). "Although the expression of AdipoR1 and AdipoR2 was previously observed in human cancer tissues, there are no clear indications about the presence of these receptors in human brain tumours." (PMID 33752745, 2021). "Both the NF-κB/IL6/JAK2/STAT3 cascade, which we show here is modulated by miR-221/222-mediated downregulation of ADIPOR1, and ZEB2 expression, which we have previously shown is repressed by TRPS1, are well-characterized effector pathways in cancer metastasis, invasion, and EMT." (PMID 23776679, 2013). "In addition, both the ADIPOR1 and ADIPOR2 exhibited extensive correlations with immune checkpoint genes in the majority of cancers, indicating that they may be used as predictors or novel targets of immunotherapy." (PMID 36896172, 2023).
tumor (34 papers, 2009 to 2025). "In summary, our findings provided evidence for the positive regulation of AdipoR1 and AdipoR2 in tumor proliferation and invasion in vitro and demonstrated an association between AdipoR1/2 and poor survival in both IHC samples and public datasets." (PMID 37454080, 2023). "PBMC ADIPOR1 downregulation again led us to question its plausible association with tumor progressive mechanisms, but now at the level of immune cells." (PMID 36429712, 2022). "Compared with the shNC group, the tumor volume of the shAdipoR1 group decreased after treatment, while that of sh-Adipor1 + IR group was smaller than that of the IR group." (PMID 39849382, 2025). "The anti-tumor impact of DCs can be diminished by AdipoR1 activating the AMPK and MAPKp38 pathways and AdipoR2 initiating the COX-2 and PPAR pathways." (PMID 36896172, 2023). "Namely, when adjacent mucosa was compared to malignantly transformed mucosa, decreased ADIPOR2 mRNA and increased ADIPOR1 mRNA levels were demonstrated in tumor tissue." (PMID 36429712, 2022). "An in silico analysis of the GSE44076 dataset showed that tumor ADIPOR1 mRNA expression was unchanged compared to the healthy tissue, while its downregulation was recorded in tumor-adjacent mucosa." (PMID 36429712, 2022). "MT tissue from MT-positive animals had significantly lower AdipoR1 protein expression levels compared to control, non-tumor, tissue obtained from the same location in MT-negative mice (p=0.002)." (PMID 32215366, 2019). "At tissue level, utilizing 16 tumor tissues, the authors observed positive or strong positive expression of AdipoR1 in 87.5% of cases while positive or strong positive expression of AdipoR2 was observed in >97% cases." (PMID 30567565, 2018). "Consistent with a previous study, the AdipoR1 and AdipoR2 expression levels significantly decreased in tumor tissues compared with surrounding normal parenchyma tissue." (PMID 28178338, 2017). "Yet, in a single-cohort study of patients affected by PTC, tumor expression of adiponectin receptors (both AdipoR1 and AdipoR2) was positively correlated with the tumor aggressiveness." (PMID 29184536, 2017). "In our cohort, AdipoR1 immunopositivity was inversely related to tumor histological grade and T category, in agreement with previous reports." (PMID 26931562, 2016). "AdipoR1, adiponectin, Ob-R and leptin were higher on score and area of staining in the tissues adjacent to the tumor than the tumor tissue." (PMID 26431176, 2015). "AdipoR1 was significantly lower in the tumor tissue than the tissues adjacent to the tumor (p = 0.027)." (PMID 26431176, 2015). "AdipoR1 was significantly higher in the tissues adjacent to the tumor (p = 0.0031) compared to the tumor tissues when considering percent of area stained whereas indifferent levels were found when compared on the staining intensity levels." (PMID 26431176, 2015). "The tumor‐suppressive effects of adiponectin are largely mediated through its receptors, adiponectin receptor 1 and adiponectin receptor 2 (AdipoR1 and AdipoR2), which activate key pathways, including AMPK and Peroxisome proliferator‐activated receptor alpha (PPAR‐α)." (PMID 40387523, 2025). "Therefore, we performed a comprehensive analysis to determine the correlation between ADIPOR1/2 and the tumor immune microenvironment." (PMID 36896172, 2023). "Only a few tumor’s ADIPOR1/2 protein data are available in the public databases." (PMID 36896172, 2023). "Referring to the TCGA, AdipoR1 mRNA level was higher in tumor as compared with normal tissues." (PMID 35733794, 2022). "In this study, we found that AdipoR1 is highly expressed in tumor cells, and its knockdown could enhance radiosensitivity of HCC cells via Nrf2-xCT signaling pathway." (PMID 35733794, 2022). "At the same time, the protective function of ADIPOR1 in tumor progression was indicated through its negative association with EMT and myogenesis in adjacent mucosa." (PMID 36429712, 2022).